ZEB1 (zinc finger E-box binding homeobox 1)
Diseases named in the same sentence as ZEB1 in open-access papers (continued):
Sharing a sentence is not in itself a finding about the gene and the disease.
tumor (continued). "ZEB1 appears to play important roles in AML cell biology, with siRNA mediated knockdown of ZEB1 in human AML cell lines leading to reduced cell proliferation and induced myeloid cell marker expression in vitro, and subsequently delayed tumor onset in in vivo xenograft models." (PMID 37600794, 2023). "ZEB1 hypermethylation was still significantly associated with longer DFS (p = 0.015) and OS (p = 0.006), irrespective of age, tumor size, stage, and blood vessel and perineural invasion." (PMID 38093305, 2023). "Cancer cells with an active CD44s-ZEB1 regulatory loop exhibited an increased tumor-sphere initiation capacity suggesting that the CD44s-ZEB1 interplay renders tumor cell stemness independent of external stimuli." (PMID 38139138, 2023). "The results showed that, overexpression of USP22 significantly promoted the growth of HCC, and knockdown of ZEB1 inhibited the effect of USP22 on tumor growth, suggesting that ZEB1 was involved in the development of HCC, and the promotion of HCC growth by USP22 was partially related to ZEB1." (PMID 36906615, 2023). "Results indicated that TRIM9 overexpression tumor cells treated with or without CQ exhibited decreased ZEB1 protein levels, whereas MG132-treated tumor cells demonstrated no such effects." (PMID 37124931, 2023). "Unexpectedly, we found high transcriptional activity of the EMT-activator ZEB1 in epithelial differentiated OSCC cells in both primary and metastatic tumor lesions, even considering that the scRNAseq data inferred transcription factor activities are biased towards transcriptional repressors." (PMID 37076857, 2023). "The ZEB1 knock-out in M13HS tumor cells was not correlated with the down-regulation of the EMT-related markers N-CADHERIN (CDH2) and VIMENTIN and up-regulation of miR-200c-3p." (PMID 38139138, 2023). "Previous studies have revealed that C2H2 zinc finger proteins such as zinc finger E-box-binding homeobox 1 (ZEB1), ZNF475 and ZNF568 could enhance tumor cell glycolysis." (PMID 36977688, 2023). "Indeed, the HS578T-Hyg and M13HS tumor hybrids expressed ZEB2, whereby markedly higher ZEB2 levels were observed in the HS578T-Hyg ZEB1-KO cells as compared to the HS578T-Hyg wildtype cells." (PMID 38139138, 2023). "Similarly, different EMT-TFs within the same family, such as ZEB1 and ZEB2, can have contrasting roles in tumor aggressiveness." (PMID 37444447, 2023). "The objective of this study was to evaluate the expression of ZEB1 and its regulation by miRNAs and genes involved in hypoxia and EMT, in addition to evaluating the potential of the two populations of tumor stem cells: ALDH+ and CD44/CD117/133 triple-positive cells." (PMID 36982993, 2023). "The Zeb1 transcription factor plays an important role in the processes of dynamic interconversion of tumor stem and non-stem cells." (PMID 37372954, 2023). "In addition, the tumor suppressor miR-217 was sponged by HOTAIR, increasing zinc finger E-box binding homeobox 1 (ZEB1) expression." (PMID 36831169, 2023). "Interestingly, we found that Zeb1 and CD206 expressions in these xenografts changed in the pattern as if LINC00963 was altered in LUAD cells, supporting the crosstalk between tumor cells and macrophages." (PMID 36604626, 2023). "Heterozygous deletion of Zeb1 in cancer mouse models blocks ZEB1’s tumor-promoting functions and further downregulation of ZEB1 does not have any additional effect on tumor formation but can prevent metastasis." (PMID 38097578, 2023). "Furthermore, the histone deacetylase HDAC6 and the zinc finger E-box-binding homeobox 1 (ZEB1) proteins were shown as differentially expressed in several cancers and are involved in tumor immune infiltration and TME." (PMID 36672310, 2023).
tumor (continued). "The IL6/JAK2/STAT3 signaling axis is best studied in the context of tumor metastasis and tumor pathology since it induces epithelial–mesenchymal transition (EMT), resulting in tumor metastasis by promoting the expression of EMT-inducing transcription factors, such as Snail, ZEB1, JunB, and Twist1." (PMID 38203502, 2023). "The researchers found that circ-0001666 acts as a sponge of miR-1251, the circRNA-associated ceRNA network further up-regulates SOX4, and circRTN4 regulates the expression of Slug, Snai1, Twist, Zeb1, and N-cadherin in the EMT pathway by interacting with tumor suppressor miR-497-5p." (PMID 35806027, 2022). "Mechanistically, TGF-β enhances pSMAD2/3 and ZEB1 and ZEB2 expression to increase tumour invasion." (PMID 36499447, 2022). "miR-1236-3p interacts with ZEB1 to inhibit the progression of LAD 20, we speculated that circRAPGEF5 could play a tumor-promoting effect through the miR-1236-3p/ZEB1 axis." (PMID 35342341, 2022). "ZEB1 plays a critical role in the regulation of DNA damage by controlling EMT in multiple tissues and modulates cancer cell differentiation and invasiveness, vascular functionality, tumor angiogenesis, and immune responses." (PMID 36402997, 2022). "Furthermore, an additional KPC model in which Zeb1 has been deleted developed PDAC anyway, although with better tumor differentiation and retained Twist1 expression despite a reduction of Zeb2, Slug and Snail expression." (PMID 36497278, 2022). "PI3K/AKT/mTOR and the other signaling pathways induce the expression of EMT-promoting transcription factors (TF) (e.g., zinc finger E-box binding homeobox 1 (ZEB1), SNAIL, TWIST), which are responsible for the eventual acquisition of mesenchymal traits by tumor cells." (PMID 35326492, 2022). "Moreover, expression of ZEB1 and the long non-coding RNA (lncRNA) linc-ZNF469-3 were correlated with TNBC tumour recurrence." (PMID 35267409, 2022). "NRP1 inhibition suppressed expression of the mesenchymal and stem cell markers ZEB1 and ITGA6, respectively, compromised spheroid-initiating capacity and exerted potent anti-tumor effects on claudin-low orthotopic xenografts (12.8-fold reduction in endpoint tumor volume)." (PMID 35078508, 2022). "In the tumor mass, we indeed observed that cancer cells stain positive for Pankeratin and E-cad and negative for Zeb1, as expected for epithelial cancer cells." (PMID 35804890, 2022). "Previous studies displayed that CSN5 could affect ZEB1 protein stability and the EMT process during tumor development via regulation of ZEB1 deubiquitination." (PMID 35342335, 2022). "Importantly, the tumor spheroids derived from the MCW-OV-SL-3 cell line expressed high levels of c-Kit, PROM1, ZEB1, SNAI, VIM, and Twist1 compared to 2D monolayer cells." (PMID 35205706, 2022). "After ERβ silencing we observed that in addition to a significant reduction of ERβ also PTEN, a tumor suppressor which can be modulated by ERβ, was reduced, while N-cadherin, vimentin, SNAIL, and Zeb-1 increased after acidic treatment, justifying the phenotype drift to a mesenchymal state." (PMID 36499700, 2022). "In concordance with a role for the tumor microenvironment and the EGFR pathway more specifically, our group reported that the strong activation of EGFR by EGF resulted in EMT induction with an up‐regulation of SNAIL, SLUG, and ZEB1." (PMID 34382739, 2022). "Therefore, we assessed the effect of cordycepin on the expression of EMT-related proteins (N-cadherin, E-cadherin, snail, and ZEB1) and matrix metalloproteinases (MMP2 and MMP9) in tumor tissues by immunohistochemistry and Western blotting." (PMID 36142286, 2022). "The upregulation of FTO further strengthens ZEB1 transcripts stability and expression by decreasing N6-methyladenosine (m6A) RNA methylation, leading to chemoresistance and epithelial-mesenchymal transition (EMT) of tumor cells." (PMID 36302751, 2022).
tumor (continued). "We further found that CP had been used as a target for four tumor drugs, while ZEB1 did not have targeted drugs yet." (PMID 35232428, 2022). "Among the many receptors expressed by the GSCs, integrin-1 and tropomyosin receptor kinase type A (TRKA) can bind to the connective tissue growth factor (CTGF) released by the astrocytes, and produce zinc finger E-box binding homeobox-1 (ZEB1), leading to tumor cell infiltration." (PMID 35562993, 2022). "In comparison, in mesenchymal (de‐differentiated) tumours, CRC cells export less miR‐200 to fibroblasts, creating a permissive environment, which allows unrepressed TGF‐β‐driven myofibroblast differentiation through ZEB1 activation." (PMID 35595718, 2022). "Thus, ZEB1 plays a key role in CCA progression by regulating tumor cell-CAF crosstalk, leading to tumor dedifferentiation and CAF activation." (PMID 36362726, 2022). "Zinc finger E-box binding homeobox (ZEB) family homeodomain transcription factors, such as ZEB1 and ZEB2, play a pivotal role in tumour progression and metastasis by induction epithelial-mesenchymal transition (EMT), with activation of stem cell traits, immune evasion and epigenetic reprogramming." (PMID 36499447, 2022). "The collected tumor samples were used to perform RT-qPCR and western blotting, revealing markedly decreased PIK3CA mRNA and protein expression in the experimental group with circ-ZEB1 downregulation as compared with that in the Sh-NC group." (PMID 35277182, 2022). "Indeed, mRNA and protein expression levels of an epithelial gene (CLDN1) were decreased, while those of mesenchymal (VIM) and EMT regulator (Snail, Twist1, ZEB1, and ZEB2) genes were increased in tumor cells." (PMID 35618735, 2022). "Regulatory mechanisms of TBX1 and the expression of ZEB1 and ZEB2 may differ among tumor types, organs, or species; however, the complete molecular mechanism underlying this effect is unknown." (PMID 36418889, 2022). "In the absence of the tumor microenvironment, Zeb1/2 levels were unaffected by Loxl3 silencing in MeL3 cells, although both gene and protein levels of Snail1 and Prrx1 EMT-TFs were markedly downregulated." (PMID 35267510, 2022). "In conclusion, this study reports that MAPKAPK5-AS1 expression is upregulated in HCC, and MAPKAPK5-AS1 acts as a tumor promoter to facilitate the proliferation, migration, invasion and EMT process of HCC cells by repressing miR-429 and upregulating ZEB1 expression." (PMID 35468721, 2022). "Taking advantage of MMP7 deficient mouse models, the EMT-related transcription factors, including Snail, Slug, Twist, Smad4 and ZEB1, and the several ECM components, including Fibronectin, Collagen, Vimentin and N-cadherin, were reduced in tumor progression and fibrotic disease model." (PMID 35659367, 2022). "As previously noted, EMT status is tightly regulated by the ZEB1/miR-200 double-negative feedback loop, and manipulation of this axis can induce an epithelial or mesenchymal shift in tumor cells." (PMID 34309585, 2021). "By analyzing the TCGA dataset, we found that miR-455 expression was significantly downregulated, while the level of ZEB1 was up-regulated in human CCA tumor tissues compared to normal samples." (PMID 34539879, 2021). "For example, the overexpression of a Snail or Zeb1 UTR without a coding gene increased endogenous Snail and Zeb1 protein expression by competing with tumor suppressive miRs." (PMID 34502497, 2021). "Even in the absence of IFNγ, activation of the miR-200/ZEB1 axis resulted in induction of T cell exhaustion in mesenchymal tumor cells, evading immune recognition and attack." (PMID 34065396, 2021). "While these data imply that ZEB1 acts as a tumor suppressor in AML, the functional requirement of Zeb1 in AML disease progression remains unknown." (PMID 33108352, 2021). "In the field of TC research, experimental data from multiple cell types have confirmed that miR-451a could suppress tumour cell proliferation and invasion by targeting PSMB8 and ZEB1." (PMID 34595349, 2021).
tumor (continued). "Moreover, LINC-ROR silencing results in the inhibition of cell proliferation, invasion, and EMT through reducing CDH1 expression and increasing the expression of ZEB1/2 and Vimentin in ESCC tumor tissues." (PMID 33745265, 2021). "As a transcriptional factor ZEB1 is an important driver of EMT and tumor progression." (PMID 33897890, 2021). "Furthermore, the expression of the ZEB1 and ZEB2 transcription factors, which are promotors of tumour invasion and metastasis, and which are direct targets of hsa-miR-200c-3p, were found to be enhanced in these cells." (PMID 34573283, 2021). "In the 80 tumors examined in this series, the number of Zeb1+ tumor cells showed weak negative correlations with the density of CD3+ CD8+ TILs while not correlated with density of TAMs." (PMID 36860286, 2021). "ZEB1 expression was downregulated in AML patients, and Zeb1 KO in the malignant counterparts of HSCs — leukemic stem cells (LSCs) — accelerated MLL-AF9– and Meis1a/Hoxa9-driven AML progression, implicating Zeb1 as a tumor suppressor in AML LSCs." (PMID 33108352, 2021). "In addition, miR-765 mimics obviously down-regulated the expression of several EMT-related markers (e.g., COL3A1, FN1, CDH2, S100A4, MMP9, SNAIL and ZEB1) and up-regulated TJP1 expression in tumor lesions." (PMID 33859750, 2021). "Finally, ZEB1, BMI1, and ALDH1A1 were highly expressed in tumor specimens from EGFR‐mutant NSCLC patients with gefitinib resistance." (PMID 33764690, 2021). "Recently, there have been two manuscripts delineating the role for ZEB1 in HSCs and their differentiation using models with Zeb1−/−, where there was an acceleration of MLL-AF9 and Meis1a/Hoxa9-driven AML progression, implicating Zeb1 as a tumor suppressor in AML LSCs." (PMID 34639154, 2021). "It suggested that CAFs and EMT-related genes, the high expressions of FN1, ZEB1 and TCF4 in the tumor microenvironment may be involved in TCM syndromes classification in CRC." (PMID 34876190, 2021). "EMT can be attained through cooperative functioning of different transcription factors such as SNAI1/2, TWIST, and ZEB1/2 with others (FOX, SOX, PRX, and HMGA2), leading to cell-forward consensus differentiations that make tumor cells capable of motility and metastasis." (PMID 34943943, 2021). "In mice lacking Zeb1, metastases were reduced in number, and the primary tumor and remaining metastatic nodules displayed a well-differentiated epithelial phenotype." (PMID 33852841, 2021). "However, similarly to GSC cultures, we found a strong association between high Gln/Glu ratios and increased expression of ZEB1 and xCT in primary GBM tumor tissue." (PMID 34885110, 2021). "In addition, ZEB1 expression was positively correlated with LINC01303, and its downregulation reversed tumor phenotype mediated by LINC01303 overexpression in vitro and in vivo." (PMID 34912458, 2021). "ZEB-1 immunohistochemical analysis showed a lack of statistical significance in the number of positive cells on the invasive front of the tumor compared with the control tissues." (PMID 34638929, 2021). "Consequently, Zeb1 upregulation impairs miRNA-200c and miRNA-141 transcription and stabilizes an EMT phenotype in tumor cells." (PMID 34771695, 2021). "ZEB1 is suggested to be upregulated and involved in the TGF-β-induced EMT, which can support metastasis and invasion of tumor cells by directly suppressing transcriptions of antifibrotic miR200c and miR141, where miR141 is an inhibitor of TGF-β as a feedback mechanism." (PMID 34299192, 2021). "Indeed, ZEB1 can induce EMT-activation and stemness by directly inhibiting several miRNAs and thereby form a feedback loop in mediating tumor development." (PMID 34163033, 2021). "Further, expression analysis of ZNF471 along with one epithelial and 9 mesenchymal markers in the GSE9750 dataset identified the downregulation of ZNF471 and CDH1 with concomitant up-regulation of ZEB1 and TWIST1 in tumor tissues when compared with normal samples (P<0.05)." (PMID 33566221, 2021).
tumor (continued). "In GBM, the overexpression of the ZEB1 gene induced the expression of MGMT, resulting in greater tumor chemoresistance and also induced the expression of SOX2 and OLIG2, resulting in greater stemness and higher capacity for tumor formation." (PMID 33762015, 2021). "Moreover, through miR-150-5p and miR-504, Linc00673 can regulate the expression of ZEB1 14 and HNF1A 16, respectively, and then exert tumor-promoting or anti-tumor activity." (PMID 33390809, 2021). "For the first time, we found that DMY significantly inhibited tumor growth and EMT by targeting the miR-455/ZEB1 axis, suggesting DMY might be explored as a potential candidate for the treatment of CCA." (PMID 34539879, 2021). "Furthermore, we found a strong association between high Gln/Glu ratios and increased expression of Zinc finger E-box-binding homeobox 1 (ZEB1) and xCT in primary GBM tumor tissues." (PMID 34885110, 2021). "Moreover, a correlation between PD-L1, ZEB1 expression and poor prognosis was found, suggesting that a cooperative mechanism bridging tumor immune avoidance and EMT contributes to tumor malignancy in ESCC." (PMID 34885101, 2021). "To answer whether ZEB1-PFKM axis contributes to tumor progression in vivo, we performed in vivo tumor formation experiment by injecting MHCC-97H cells into the same site of the left liver lobe of nude mice to develop orthotopic liver tumor." (PMID 33897890, 2021). "Analysis of ZEB1 gene transcription demonstrated that metastatic lesions express less ZEB1 than corresponding primary tumours, but more of miR‐200 suggesting this negative feedback loop is effective in the MET process at secondary CRC." (PMID 33931939, 2021). "FACS analysis of the primary tumor revealed an increase in EpCAMlo cells from 4.8% in the non-induced tumors up to 22–76% upon dox-induction of Zeb1 expression." (PMID 34036938, 2021). "Also, YAP1 can interact with ZEB1 in the EMT process, which favors tumor progression and metastasis in WT." (PMID 32766179, 2020). "Given that OVOL1/2 inhibited the expression of EMT-related factors such as vimentin and ZEB1, we hypothesized that knockdown of OVOL1 or OVOL2 may enhance tumor cell invasion." (PMID 32106476, 2020). "We then proved the anti-tumor role of miR-432-3p in CRC, showing that the inhibitory effect of AC010789.1 knockdown on CRC cells was achieved by the upregulation of miR-432-3p but downregulation of ZEB1." (PMID 33178684, 2020). "The deletion of Twist1 or Snai1 alone was not sufficient to suppress EMT, while the deletion of ZEB1 had a greater impact on the tumour phenotype and metastasis." (PMID 33207810, 2020). "In the present study, the clinical importance of ZEB1 expression and its correlation with AR expression were assessed in GC using tumor and adjacent non-tumor tissues from GC patients, normal gastric tissues from normal cases and two GC cell lines." (PMID 32153739, 2020). "In certain tumor cells, SNAI1 upregulates ZEB1 and ZEB2 expression." (PMID 32226439, 2020). "They found that in diffuse large B lymphoma, increased expression of lnc-SNHG14 could promote ZEB1 expression through sponge adsorption of miR-5590-3p and further activate PD-L1 and inhibit CD8+ T cells to promote the immune escape of tumor cells." (PMID 33194692, 2020). "Notably, miRNA-205 (miR-205) contributes to tumour vascularization and tumour invasion through regulating the expression of VEGF-A and ZEB1 genes in melanoma, glioblastoma, ovarian carcinoma, and breast carcinoma." (PMID 33126409, 2020). "Previous studies have demonstrated that miR-484 can reduce the expression of a series of oncogenes, such as ZEB1, SMAD2, etc., inhibit the epithelial-mesenchymal transition (EMT) of tumor cells, or regulate the extracellular signal-regulated kinase 1/2 signaling." (PMID 32192507, 2020).